FLT3 (fms related receptor tyrosine kinase 3)
Diseases named in the same sentence as FLT3 in open-access papers (continued):
Sharing a sentence is not in itself a finding about the gene and the disease.
acute myeloid leukemia (continued). "In order to confirm our findings in a second oncogenic model of acute myeloid leukemia, we crossed FLT3-ITD knock-in mice with transgenic animals expressing the interferon inducible Mx1-Cre-recombinase and the conditional Llgl1 knockout." (PMID 37587260, 2023). "Several FLT3 inhibitors(i) are available to treat relapsed/refractory (R/R) FLT3‐internal tandem duplicated acute myeloid leukemia (AML)." (PMID 36819163, 2023). "By promoting autophagy and apoptosis mediated by mTOR, metformin sensitizes FLT3-ITD-positive acute myeloid leukemia to sorafenib." (PMID 37842232, 2023). "Herein we present a class of drug-delivery nanocompounds based on TKI Midostaurin-loaded gold nanoparticles that have the potential to be used as theranostic agents for the targeting of the FMS-like tyrosine kinase 3 (FLT3) in acute myeloid leukemia." (PMID 37623644, 2023). "The outcomes of FLT3-ITD acute myeloid leukaemia (AML) have been improved since the approval of FLT3 inhibitors (FLT3i)." (PMID 37019911, 2023). "For example, an ITD occurring predominantly in exon 14 of the receptor tyrosine kinase, FLT3, is a well-established prognostic marker for acute myeloid leukemia." (PMID 37686670, 2023). "Eventually, it was found that compound 27 can suppress in dose-relevant mode phosphorylation of both ERK1/2 and mTOR in FLT3-ITD acute myeloid leukemia cells." (PMID 37438819, 2023). "For example, USP10 is the important deubiquitinase required to stabilize oncogenic forms of the kinase FLT3, a critical therapeutic target in acute myeloid leukemia (AML)." (PMID 37072811, 2023). "FLT3-ITD up-regulates MCL-1 to promote the survival of stem cells in acute myeloid leukemia via FLT3-ITD-specific STAT5 activation." (PMID 37892567, 2023). "Currently, two FLT3 inhibitors are approved for use in patients with acute myeloid leukemia: midostaurin in the frontline setting, in combination with intensive chemotherapy; and gilteritinib as monotherapy in the relapsed refractory setting." (PMID 37190240, 2023). "The insertion site of the internal tandem duplications (ITDs) in the FLT3 gene affects the sensitivity to tyrosine kinase inhibitors (TKIs) therapy in acute myeloid leukemia (AML)." (PMID 36509894, 2023). "In 2022, the European LeukemiaNet (ELN) risk classification system for acute myeloid leukemia patients modified risk genes including CEBPA mutation status, myelodysplasia‐related gene mutations and internal tandem duplications of FLT3 (FLT3‐ITD)." (PMID 38098254, 2023). "In acute myeloid leukemia (AML) with internal tandem duplications of fms-like tyrosine kinase 3 (FLT3-ITD), PARP1 is indispensable for STAT5 activity through interacting and PARylating STAT5 to prevent its proteasomal degradation." (PMID 36909172, 2023). "It acts as an inhibitor of FMS-like tyrosine kinase 3 (FLT3) and has been evaluated in various clinical trials against acute myeloid leukemia." (PMID 36677600, 2023). "The patient was diagnosed with acute myeloid leukemia (AML)-M5b accompanied by DNMT3A, FLT3-TKD, and IDH2 mutations, chest CT revealed pulmonary tuberculosis (TB)." (PMID 37384044, 2023). "Acute myeloid leukaemia (AML) is characterized by the most prevalent genetic alteration, the type III receptor Fms-like tyrosine kinase 3 (FLT3) mutation, which affects around one-third of AML patients." (PMID 37645444, 2023). "Molecularly targeted therapy is now a standard treatment option for patients with acute myeloid leukemia and IDH1/2 or FLT3 mutations." (PMID 36900407, 2023). "The fms like tyrosine kinase 3–mutant (FLT3-mutant) acute myeloid leukemia (AML) cell line MOLM-13 fulfills these criteria." (PMID 37681415, 2023). "Several studies have investigated the resistance to FLT3 inhibitors in acute myeloid leukemia (AML) and data from CRISPR screens has provided a better understanding of synergistic partners as well as potential biomarkers." (PMID 37875911, 2023).
acute myeloid leukemia (continued). "Gilteritinib is indicated for the treatment of acute myeloid leukemia deriving from an FMS-like tyrosine kinase gene (FLT3) mutation detected by a companion diagnostic; it is a dual FLT3/AXL selective inhibitor." (PMID 38202651, 2023). "It has been demonstrated that circMYBL2 controls FLT3 translation by recruiting PTBP1 to promote the progression of FLT3-internal tandem duplication acute myeloid leukemia." (PMID 37065445, 2023). "Acute myeloid leukemia (AML) patients with FLT3-ITD mutations are associated with poor prognosis." (PMID 36739272, 2023). "The presence of FLT3-ITD is among the most common molecular aberrations in acute myeloid leukemia (AML)." (PMID 36831653, 2023). "The FMS-like tyrosine kinase-3 (FLT3) is mutated in ~30% of acute myeloid leukemia (AML) patients." (PMID 37735559, 2023). "FLT3 is the most frequently mutated gene in acute myeloid leukemia (AML), with FLT3 internal tandem duplication (ITD) mutations being associated with a more aggressive clinical course." (PMID 37696819, 2023). "FLT3-ITD is the most common driver mutation, with approximately 30% in acute myeloid leukaemia (AML), and is associated with poor clinical outcomes." (PMID 37019911, 2023). "This phenomenon suggests that IGF2BP2 can affect the progression of FLT3-ITD + acute myeloid leukemia." (PMID 37060505, 2023). "The prognosis of acute myeloid leukemia depends on genetic aberrations, particularly NPM1 and FLT3-ITD mutations." (PMID 36230640, 2022). "Conditioned media of human bone marrow stromal cells (hBMSCs) prevents apoptosis in FLT3-ITD acute myeloid leukemia (AML) cells upon FLT3 inhibition." (PMID 36259537, 2022). "The potency of compound 6 was further demonstrated from the induction of cell death via necrosis in FLT3-ITD mutant and FLT3-inhibitor resistant cell lines and primary blasts from acute myeloid leukemia (AML) patients." (PMID 35408693, 2022). "Here, the authors show that FLT3-ITD + acute myeloid leukemia cells are OXPHOS-driven, and inhibition of complex II activity results in increased lactate influx to drive respiration, which creates a targetable vulnerability." (PMID 35440568, 2022). "Internal tandem duplication of the FMS‐like tyrosine kinase 3 (FLT3‐ITD) is one of the most common and clinically relevant mutations in acute myeloid leukemia (AML)." (PMID 35846029, 2022). "The aim of this study was to investigate the effect of sorafenib maintenance post-transplantation on the incidence and mortality of EBV and CMV infections in patients with FLT3-ITD acute myeloid leukemia." (PMID 36050712, 2022). "The aim of this study was to characterize the mutational landscape of patients with FLT3-mutated acute myeloid leukemia (AML) treated within the randomized CALGB 10603/RATIFY trial evaluating intensive chemotherapy plus the multi-kinase inhibitor midostaurin versus placebo." (PMID 35922444, 2022). "Acute myeloid leukemia (AML) often occurs due to chromosomal abnormalities or mutations in the genes NPM1, CEPBA, RUNX1 and FLT3 and is characterized by an over-accumulation of abnormal cells called myeloblasts." (PMID 35159109, 2022). "While acute myeloid leukemia (AML) is still associated with a low cure rate, recent advances in understanding its molecular complexity have significantly improved therapy for subgroups of patients, including those harboring FLT3, IDH1, or IDH2 mutations." (PMID 35354920, 2022). "Treating acute myeloid leukemia (AML) by targeting FMS-like tyrosine kinase 3 (FLT-3) is considered an effective treatment strategy." (PMID 36504722, 2022). "Internal tandem duplication (ITD) in the fms-like tyrosine kinase 3 (FLT3) gene is the most common abnormalities in acute myeloid leukemia (AML) with a range of approximately 5–15% of children and 25–35% of adults." (PMID 36407352, 2022).
acute myeloid leukemia (continued). "Nonetheless, this postulation has been recently challenged by a report of inhibition of FMS-Like Tyrosine Kinase 3-Internal Tandem Duplication (FLT3-ITD) in resistant acute myeloid leukemia (AML) cells." (PMID 35669422, 2022). "pHASED was optimized using tyrosine kinase inhibitor (sorafenib) resistant isogenic FLT3-mutant acute myeloid leukemia (AML) cell line models." (PMID 36536316, 2022). "Crenolanib is a second-generation FLT3 inhibitor that is now being tested in clinical studies for its safety and efficacy in the treatment of several cancers, including acute myeloid leukemia (AML) and gastrointestinal stromal tumors (GIST)." (PMID 35566032, 2022). "ASP2215 is a highly selective, dual AXL/FLT3 (FMS-like tyrosine kinase 3) inhibitor that showed anti-leukemic activity in relapsed or refractory acute myeloid leukemia (AML) patients." (PMID 35311091, 2022). "Autophagy plays a critical role in drug resistance in acute myeloid leukemia (AML), including the subtype with FLT3-ITD mutation." (PMID 35794565, 2022). "The emergence of metabonomics has prompted the exploration of the mechanisms driving FLT3-ITD acute myeloid leukemia resistance to FLT3 inhibitors from a new perspective." (PMID 36185253, 2022). "SF3B1 and mutations in it have been exploited extensively as a therapeutic target in FLT3/ITD positive acute myeloid leukemia (AML), endometrial cancer, and hepatocellular carcinoma." (PMID 35230971, 2022). "Internal tandem duplications (ITD) in the receptor tyrosine kinase FLT3 occur in 25 % of acute myeloid leukemia (AML) patients, drive leukemia progression and confer a poor prognosis." (PMID 35999260, 2022). "The treatment of acute myeloid leukemia (AML) has been rapidly evolved from conventional chemotherapy to target therapeutics such as FLT3-ITD and IDH2 inhibitors, thereby improving the complete remission rates over the past decade." (PMID 36355485, 2022). "Targeting the mTOR pathway reverses the bone marrow (BM)-mediated protection of FLT3-ITD acute myeloid leukemia (AML) cells from FLT3 inhibition." (PMID 36259537, 2022). "This leukemia subtype shows a higher prevalence of mutations, typically associated with acute myeloid leukemia (AML), including RAS and FLT3 mutations." (PMID 35626079, 2022). "Internal tandem duplication of the Feline McDonough Sarcoma (FMS)‐like tyrosine kinase 3 (FLT3‐ITD) is one of the most clinically relevant mutations in acute myeloid leukemia (AML), with a high FLT3‐ITD allelic ratio (AR) (≥0.5) being strongly associated with poor prognosis." (PMID 35846029, 2022). "Midostaurin (PKC412) has been used in the clinical treatment of fms-like tyrosine kinase 3 (FLT3)-mutant acute myeloid leukemia and has demonstrated immunomodulatory activity." (PMID 36230769, 2022). "FLT3 is best described for its pivotal role in the constitutive activation and development of acute myeloid leukemia (AML) in humans." (PMID 35887060, 2022). "Therapy of FLT3-positive acute myeloid leukemia still remains complicated, despite the availability of newly approved kinase inhibitors." (PMID 36555810, 2022). "FLT3 alterations were studied mostly in acute myeloid leukemia, and are particularly involved in cell differentiation, survival, and proliferation, in a mechanism involving PI3K, RAS, and STAT5." (PMID 35330454, 2022). "Midostaurin has a broad inhibition spectrum, with many kinases, beyond KIT, among its targets (for example, being also a Flt3 inhibitor, it is used also in acute myeloid leukemia)." (PMID 35159005, 2022). "Fms-like tyrosine kinase 3 (FLT3) is a significant target for treating acute myeloid leukemia (AML)." (PMID 35337118, 2022). "Blasts with cup‐like morphology are well recognized in acute myeloid leukemia (AML), being frequently associated with a normal karyotype and mutated NPM1 and/or FLT3‐ITD." (PMID 36051070, 2022).
acute myeloid leukemia (continued). "This analysis aimed to systematically review and synthesize the existing evidence regarding the outcome of tyrosine kinase inhibitor (TKI) maintenance therapy after allogeneic stem-cell transplantation for patients with FLT3-ITD-mutated acute myeloid leukemia (AML)." (PMID 33790903, 2021). "G-749 is an FLT3 kinase (FMS-like tyrosine kinase 3, FLT3) inhibitor, which was originally developed as a treatment for acute myeloid leukemia (AML) and later designated as an orphan drug by the Federal Drug Administration (FDA) in 2018." (PMID 34721022, 2021). "Approximately 30% of adult acute myeloid leukemia (AML) acquire within fms-like tyrosine kinase 3 gene (FLT3) internal tandem duplications (FLT3/ITDs) in their juxtamembrane domain (JMD)." (PMID 33494808, 2021). "FMS-like tyrosine kinase 3 (FLT3) has emerged as a rational therapeutic target in acute myeloid leukemia (AML)." (PMID 33415416, 2021). "Improved therapies are likewise necessary for poor-prognosis acute myeloid leukemia (AML) patients with internal tandem duplication in the FMS-like tyrosine kinase (FLT3-ITD)." (PMID 34298678, 2021). "Recurrent somatic internal tandem duplications (ITD) in the FMS‐like tyrosine kinase 3 (FLT3) gene characterise approximately one third of patients with acute myeloid leukaemia (AML), and FLT3‐ITD mutation status guides risk‐adapted treatment strategies." (PMID 33817952, 2021). "RSK2, a critical serine/threonine-protein kinase that acts downstream of ERK in FLT3-ITD-acute myeloid leukemia (AML), was also identified as another PIM2 target." (PMID 34770845, 2021). "FLT3 as a key therapeutic target is one of the most commonly dysregulated driver oncogenes in acute myeloid leukemia, and other hematologic malignancies." (PMID 33574356, 2021). "Yet, several mutations in the FLT-3 gene have been identified in acute leukemias, and serum FLT-3L was shown to be a useful marker in the classification of acute myeloid leukemia." (PMID 34248946, 2021). "It is not clear how Fms-like tyrosine kinase 3-internal tandem duplications (FLT3-ITD) regulates checkpoint kinase 1 (CHK1) in acute myeloid leukemia (AML)." (PMID 34168220, 2021). "FMS-like tyrosine kinase 3 (FLT3) mutant acute myeloid leukemia (AML) occurs in approximately 30% of all AML patients and still has a poor prognosis." (PMID 34594375, 2021). "A recent study demonstrated that glucocorticoids (GCs) enhance the antileukemic activity of FLT3 inhibitors in FLT3-mutant acute myeloid leukemia." (PMID 33577442, 2021). "In the past 2 decades since FLT3-ITD and TKD mutations were identified in acute myeloid leukemia, researchers have continued unremitting exploration on FLT3-targeted therapies." (PMID 34760927, 2021). "Acute myeloid leukemia (AML) with Fms-like tyrosine kinase 3 internal tandem duplication (FLT3-ITD) represents a large and heterogeneous group of patients associated with unfavorable prognosis." (PMID 34876631, 2021). "Notably, FLT3 has a prominent role in the hematologic malignancies, with one-third of adult acute myeloid leukemia (AML) patients presenting with activating mutations in FLT3, and wild-type FLT3 being found overexpressed in hematologic malignancies." (PMID 33462189, 2021). "Previously, miR-1229 was reported to participate in the viability and apoptosis of FLT3-ITD-positive acute myeloid leukemia cells." (PMID 33854621, 2021). "For that we used four human cell lines: K562—chronic myeloid leukemia cell line; MV4;11—acute myeloid leukemia cell line, bearing mutant FLT3; U937 cells, widely used as a model for monocytic leukemia study; THP-1—acute monocytic leukemia cells." (PMID 34564151, 2021). "Furthermore, the accompanying mutations and fusion genes with FLT3 mutations are unclear in acute myeloid leukemia (AML)." (PMID 33836835, 2021). "FLT3 gene alterations occur frequently in acute myelogenous leukemia cases and sporadically in other myeloproliferative diseases." (PMID 34799652, 2021).
acute myeloid leukemia (continued). "Internal tandem duplications (ITD) in the FMS‐like tyrosine kinase 3 (FLT3) gene is present in 20–30% of acute myeloid leukaemia (AML) patients." (PMID 33817952, 2021). "Quizartinib is a once-daily, oral, highly potent, and selective, second-generation, type II FLT3 inhibitor that has shown antitumor activity in FLT3-ITD acute myeloid leukemia in animal models." (PMID 34070902, 2021). "Acute myeloid leukemia (AML) with fms-like tyrosine kinase 3 internal tandem duplication (FLT3-ITD) relapses with new chromosome abnormalities following chemotherapy, implicating genomic instability." (PMID 34504649, 2021). "circMYBL2 has been reported to regulate FMS-like tyrosine kinase-3 (FLT3) translation by recruiting polypyrimidine tract-binding protein 1 (PTBP1) to promote FLT3-internal tandem duplication in acute myeloid leukemia progression." (PMID 34322012, 2021). "Targeting CDK1 has been reported to promote FLT3-activated acute myeloid leukemia differentiation in cell lines as well as in patient blood samples." (PMID 34067359, 2021). "Although a role for Notch in regulation of Flt3 in homeostatic lymphopoiesis has yet to be established, canonical Notch target Hes1 transcriptionally represses Flt3 expression in Acute Myeloid Leukemia (AML)." (PMID 34394130, 2021). "These include Ruxolitinib, a janus kinase 1/2 inhibitor for Primary Myelofibrosis and Polycythemia Vera, Ibrutinib, a bruton kinase inhibitor for B-cell malignancies and most recently Midostaurin, a multi-kinase inhibitor for FMS-like tyrosine kinase 3 (FLT3) mutated acute myeloid leukemia (AML)." (PMID 34238254, 2021). "One of the most common genetic alterations is the gatekeeper T315I substitution observed in chronic myeloid leukemia (CML) or Philadelphia chromosome positive (Ph+) acute lymphoblastic leukemia (ALL) and FMS-like tyrosine kinase-3 (FLT3)-activating mutations in acute myeloid leukemia (AML)." (PMID 35008250, 2021). "FLT3-internal tandem duplication occurs in ~20–30% of acute myeloid leukemia resulting in constitutive activation and abnormal cellular proliferation." (PMID 31471587, 2020). "All 136 FLT3-internal tandem duplication-positive cases demonstrated a confirmed diagnosis (internal cases) or clear test indication (outside cases) of acute myeloid leukemia." (PMID 31471587, 2020). "This study aimed to investigate the correlation between GM-CSF gene expression and different molecular prognostic markers such as FLT3-ITD, NPM1 mutation A and CEBPA gene expression in Egyptian acute myeloid leukemia patients." (PMID 32711425, 2020). "The fms-like tyrosine kinase 3 internal TD (FLT3-ITD) is present in 30% of cases of acute myeloid leukemia (AML)." (PMID 32849857, 2020). "In the current study, we retrospectively investigated the characteristics and real-world outcomes of R/R FLT3-internal tandem duplication (ITD) acute myeloid leukemia (AML) patients in the Toulouse-Bordeaux DATAML registry." (PMID 32722211, 2020). "Acute myeloid leukemia (AML) with co-existing NUP98-NSD1 and FLT3-ITD mutation is accompanied by poor prognosis and a low chance of survival." (PMID 33381025, 2020). "The phase III ADMIRAL trial showed improved overall survival with the gilteritinib vs salvage chemotherapy in patients with Flt3-mutated acute myeloid leukemia, making gilteritinib a routine therapy for adult AML patients who have relapsed or refractory diseases with a Flt3 mutation." (PMID 33363015, 2020). "In the present review, we will summarize the current knowledge of SFK functions in acute myeloid leukemia and mastocytosis, with a focus on oncogenic FLT3 and KIT receptor signaling." (PMID 32708273, 2020). "Midostaurin is reported to inhibit activating mutant forms of the human FMS-like tyrosine kinase-3 (FLT3) and is approved for the treatment of acute myeloid leukaemia bearing FLT3 activating mutations; it inhibits >90% AspH activity at 20 μM (entry 6)." (PMID 33069066, 2020).